TERF1 (telomeric repeat binding factor 1)
Description:
Binds the telomeric double-stranded 5'-TTAGGG-3' repeat and negatively regulates telomere length. Involved in the regulation of the mitotic spindle. Component of the shelterin complex (telosome) that is involved in the regulation of telomere length and protection. Shelterin associates with arrays of double-stranded 5'-TTAGGG-3' repeats added by telomerase and protects chromosome ends; without its protective activity, telomeres are no longer hidden from the DNA damage surveillance and chromosome ends are inappropriately processed by DNA repair pathways.
Synonyms: PIN2; TRBF1; TRF; TRF1; hTRF1-AS; t-TRF1
Tractability: Small molecule: it has a binding pocket of medium quality. PROTAC: UniProt records ubiquitination sites on it; ubiquitination databases record sites on it; its protein half-life has been measured.
Gene: Protein-coding gene on chromosome 8 (73,008,833 to 73,048,123, forward strand). Ensembl gene ENSG00000147601.
Subcellular location: Nucleus; Cytoplasm, cytoskeleton, spindle; Chromosome, telomere
Subcellular location (Human Protein Atlas): Nucleoli fibrillar center; Nuclear bodies
Pathways (Reactome):
Cell Cycle: Inhibition of DNA recombination at telomere; Packaging Of Telomere Ends; Polymerase switching on the C-strand of the telomere; Processive synthesis on the C-strand of the telomere; Removal of the Flap Intermediate from the C-strand; Telomere C-strand (Lagging Strand) Synthesis; Telomere C-strand synthesis initiation; Telomere Extension By Telomerase
DNA Repair: Cleavage of the damaged purine; Cleavage of the damaged pyrimidine; Recognition and association of DNA glycosylase with site containing an affected purine; Recognition and association of DNA glycosylase with site containing an affected pyrimidine
Cellular responses to stimuli: DNA Damage/Telomere Stress Induced Senescence
Reproduction: Meiotic synapsis
Gene Ontology:
Molecular function: ankyrin repeat binding; DNA binding, bending; double-stranded telomeric DNA binding; G-rich strand telomeric DNA binding; identical protein binding; protein binding; protein homodimerization activity; telomerase activity; telomeric DNA binding; DNA binding
Biological process: negative regulation of DNA replication; negative regulation of establishment of protein localization to telomere; negative regulation of establishment of RNA localization to telomere; negative regulation of telomere maintenance via telomerase; negative regulation of telomeric D-loop disassembly; positive regulation of shelterin complex assembly; telomere capping; telomere maintenance; telomere maintenance via telomerase; telomeric D-loop disassembly; negative regulation of establishment of protein-containing complex localization to telomere; negative regulation of telomere maintenance via semi-conservative replication; negative regulation of telomere maintenance via telomere lengthening; positive regulation of telomere maintenance; t-circle formation; response to xenobiotic stimulus
Cellular component: chromosome, telomeric region; nuclear body; nuclear telomere cap complex; nucleolus; nucleus; shelterin complex; nucleoplasm; spindle
Genetic constraint (gnomAD): Loss-of-function variants: 5 observed, 17.51 expected, observed/expected ratio (o/e) 0.29, 90% interval 0.15 to 0.6. The upper end of that interval is the gene's LOEUF score, 0.6, which puts it in group 2 of 6, group 1 being the genes least tolerant of losing a copy. Missense variants: 242 observed, 255.4 expected, observed/expected ratio (o/e) 0.95, 90% interval 0.85 to 1.05. Synonymous variants: 95 observed, 94.99 expected, observed/expected ratio (o/e) 1, 90% interval 0.85 to 1.19.
Homologues: Orthologues: chimpanzee TERF1 (98% identical), macaque TERF1 (97% identical), pig TERF1 (84% identical), dog TERF1 (80% identical), guinea pig TERF1 (70% identical), rat Terf1 (65% identical), mouse Terf1 (64% identical), tropical clawed frog terf1 (35% identical), zebrafish terf1 (23% identical). Paralogues in human: TERF2 (24% identical).